CDK4 (cyclin dependent kinase 4)
Diseases named in the same sentence as CDK4 in open-access papers (continued):
Sharing a sentence is not in itself a finding about the gene and the disease.
triple-negative breast carcinoma (79 papers, 2016 to 2026). An invasive breast carcinoma which is negative for expression of estrogen receptor (ER), progesterone receptor (PR), and human epidermal growth factor receptor 2 (HER2). "For instance, RNF181 can modulate signaling pathways that involve Hippo/YAP, CARD11 and ERK/MAPK-cyclin D1/CDK4, and it has been implicated in diseases like triple negative breast cancer and gastric cancer." (PMID 41494040, 2026). "Meanwhile, the keywords “cdk4”, “triple negative breast cancer”, “esr1 mutations” and “multicenter” appeared in recent years." (PMID 37637052, 2023). "Emerging topics such as “cdk4”, “triple negative breast cancer”, “esr1 mutations”, and “multicenter” need further research." (PMID 37637052, 2023). "Inhibition of CDK2 and CDK4/6 functions has been found to suppress the growth of triple negative breast cancer cells (TNBC), which manifests itself in loss of expression of the RB protein, or high expression of cyclin E, which are thought to confer resistance to treatment with CDK4/6 inhibitors." (PMID 33805800, 2021). "Previous study by Asghar U indicated that a subset of triple-negative breast cancer cells with expression of AR and the loss of cyclin E1 could be responsive to CDK4/6 inhibition." (PMID 28438180, 2017). "Indeed, inhibition of CDK4 in a triple-negative breast cancer cell line caused decreases in the EMT-associated transcription factors Snail and Twist and decreases in phosphorylated Smad3." (PMID 27167191, 2016). "Functional loss of RB1 is a common genetic alteration in triple-negative breast cancer (TNBC) and is associated with poor response to targeted therapies, including CDK4/6 inhibitors." (PMID 41285729, 2025). "CDK4/6 inhibitors (CDK4/6i) have improved cancer patient outcomes but shown limited benefits for those with triple-negative breast cancer (TNBC)." (PMID 39788939, 2025). "MDA-MB-231 triple negative breast cancer cells were chosen due to their high sensitivity to CDK4/6 inhibition." (PMID 40894871, 2025). "Specifically, SPS have been shown to induce cell cycle arrest at the G0/G1 phase by down-regulating CDK4 and cyclin D1 while up-regulating p21 protein expression in triple-negative breast cancer cells (MDA-MB-231)." (PMID 40507156, 2025). "In their experiment with a triple-negative breast cancer cell line, they obtained an optimal CDK4 degradation in 4 h and a maximal decomposition of CDK6 in 6 h after treating the cells with 100 nM degrader concentration." (PMID 39598723, 2024). "A furyl derivative of palbociclib exhibited the highest potency against the MDA-MB-453 cell line (triple-negative breast cancer) cell line, preserved selectivity to CDK4/6, and exhibited better stability in the mouse liver microsome assay than palbociclib." (PMID 39598723, 2024). "The presented PROTAC that is based on KB02 ligand degrades CDK4/6, inhibits the proliferation of triple-negative breast cancer cells (MDA-MB-231), and exhibits therapeutic potential in the xenograft model in vivo." (PMID 39598723, 2024). "Recent advances in triple-negative breast cancer research revealed that inhibition of the CDK4/6 pathway with palbociclib in the triple-negative breast cancer cell line enhances the antiproliferative effect of cisplatin." (PMID 39598723, 2024). "Although a role for ACAA1 in gastric cancer has not been clarified, researchers observed that ACAA1 down-regulation inhibited the proliferation of triple-negative breast cancer cells and enhanced their response to CDK4/6 inhibitors." (PMID 38406279, 2024).
triple-negative breast carcinoma (continued). "Knockdown of ZNF703 in triple-negative breast cancer cells was shown to inhibit the expression of cyclin D1, CDK4, CDK6, and E2F1 and upregulation of Rb1." (PMID 37686244, 2023). "The HR-/HER2- group, as the triple-negative breast cancer type, was considered resistant to CDK4/6i with higher ‘‘p-YB-1/PARP1’’ expression." (PMID 38037159, 2023). "It has been reported that the synergy of PI3K and CDK4/6 inhibitors increases apoptosis and cell cycle arrest in triple-negative breast cancer cells, and that tumor immunogenicity is enhanced." (PMID 35880418, 2022). "A common observation in a subset of Triple Negative Breast Cancers (TNBCs) is that prolonged CDK4/6 inhibition can engage a senescence-like state where cells exit the cell cycle, whilst, remaining metabolically active." (PMID 35817775, 2022). "CDK4 inhibition in triple-negative breast cancer reversed the EMT status of cancer cells, as seen in the mesenchymal-like KP tumors treated with palbociclib in the present study." (PMID 34309585, 2021). "Studies on MDA-MB-231, a triple negative breast cancer cell line, showed that CDK4 is degraded more efficiently and PROTAC containing palbociclib (22a) is more potent (DC50 CDK4 = 12.9 nM, DC50 CDK6 = 34.1 nM) than 22b (DC50 CDK4 = 97 nM, DC50 CDK6 = 300 nM)." (PMID 33803309, 2021). "One study investigated the role of lysosomal activity in triple-negative breast cancer cells, which are resistant to CDK4/6 inhibitors." (PMID 34830174, 2021). "Recently, it has been revealed that the inhibition of PI3K, JAK/STAT and CDK4/6 pathways improve the infiltration of cytotoxic CD8+ T type TILs in mouse models with triple-negative breast cancer." (PMID 34257359, 2021). "The CDK4/6 inhibitor palbociclib (PD0332991) can reduce triple-negative breast cancer (TNBC) metastasis via inducing the inactivation of DUB3." (PMID 30935108, 2019). "Here the authors show that inhibition of CDK4/6 blocks tumour metastasis in triple negative breast cancer by targeting DUB3 which in turns deubiquitinates and stabilises SNAIL1." (PMID 28067227, 2017). "More recently, our publication showed that the combination of silencing CDK4 and ionizing irradiation in triple negative breast cancer cells MDA-MB-231 and MDA-MB-468 lowered phospho-Bad-Ser136 levels and increased PP2A, which resulted in apoptosis." (PMID 29100415, 2017). "In this study, we found the cyclin-dependent kinase (CDK4) to act as a cancer stem cell regulator and novel prognostic marker in triple negative breast cancers." (PMID 27759034, 2016). "This gene repression program was conserved in an aggressive triple negative breast cancer xenograft, indicating that this is a common feature of CDK4/6 inhibition." (PMID 27564114, 2016). "While CDK4 is known for its role in cell proliferation, its metabolic function in cancer, particularly in triple-negative breast cancer (TNBC), remains unclear." (PMID 39788939, 2025). "Importantly, sequential treatment with CDK4/6i and lysosomotropic agents effectively reduces the growth of both hormone receptor-positive (HR+) and subsets of triple-negative breast cancer (TNBC) cells in vivo." (PMID 39930269, 2025). "However, their long-term efficacy is limited by acquired resistance, and CDK4/6i monotherapy remains ineffective in triple-negative breast cancer (TNBC)." (PMID 40794455, 2025). "In hormone receptor (HR) positive and human epidermal growth factor receptor 2 (HER2)-triple-negative breast cancer, the overexpression of CDK4 and 6 can lead to uncontrolled cell proliferation that may evolve into malignant tumors." (PMID 38856753, 2024). "Furthermore, CDK4/6 inhibitors have been reported to arrest the cell cycle via a hormone-receptor-independent mechanism in the luminal androgen receptor type of triple-negative breast cancer." (PMID 37158934, 2023).
triple-negative breast carcinoma (continued). "A role for CDK4 in glycolysis has been described in mouse embryonic fibroblasts (MEFs), whereby CDK4 knockout impairs anaerobic glycolysis, whilst the CDK4/6 inhibitor palbociclib reduces glycolysis in triple-negative breast cancer and mesothelioma." (PMID 33572972, 2021). "Fascinatingly, there is a subset of triple-negative breast cancer cells that actually does rely on CDK4/6 for proliferation, which implies that targeting CDK4/6 could be a therapeutic option for such patients." (PMID 34830174, 2021). "Furthermore, our data indicate the potential use of CDK4/6 inhibitors in the treatment of triple-negative breast cancer (TNBC)." (PMID 32296027, 2020). "Until recently, CDK4/6 inhibitors have not been investigated in patients with HER2+ or triple negative breast cancers, which portend the highest risk of brain metastases." (PMID 31695840, 2019). "We found CDK4 to be highly expressed in these tumors and its expression to correlate with poor overall and relapse free survival outcomes, high tumor grade and poor prognostic features of triple negative breast cancer patients." (PMID 27759034, 2016). "Finally, blocking CDK4 activity efficiently eliminated both normal and chemotherapy-resistant cancer cells in triple negative breast cancers, highlighting CDK4 as a promising novel therapeutic target for these aggressive breast tumors." (PMID 27759034, 2016). "Likewise, a phase II trial in patients with metastatic triple-negative breast cancer confirmed that administration of CDK4/6is before chemotherapy could enhance T-cell activation and improve overall survival in patients." (PMID 39593745, 2024). "In addition, the dual blockade of PI3Ka and CDK4/6 not only significantly enhanced the induction of apoptosis, cell-cycle arrest, and tumor immunogenicity but also induced immunogenic cell death in human triple-negative breast cancer (TNBC) cells." (PMID 39593745, 2024). "Our previous study has also established that CDK4/6 phosphorylates DUB3 at Ser41, leading to the stabilization of Snail1 and promoting triple negative breast cancer metastasis." (PMID 40307228, 2025). "The cornerstone of treatment is systemic therapy: hormone therapy in HR-positive subtypes (especially in combination with CDK4/6 inhibitors), targeted therapy for HER2-positive tumors, and chemotherapy for triple-negative breast cancer." (PMID 40746598, 2025). "Chemotherapeutics for targeting CDK4 and CDK6 like Palbociclib (PAB) in triple-negative breast cancer was widely explored." (PMID 36051857, 2022). "Previous studies have shown that BET inhibition synergizes with CDK4/6 inhibitors in NUT midline carcinoma and triple-negative breast cancer through aneuploidy-induced cell cycle arrest." (PMID 35881485, 2022). "One emerging approach involves selective CDK4 inhibitors to serve as myeloid-protective agents in retinoblastoma (RB)-negative tumours, such as triple-negative breast cancer (TNBC)." (PMID 40478388, 2025). "Due to the limitations of CDK4/6is in triple-negative breast cancer (TNBC), a CDK4/6i polyamino acid nanoparticle formulation, named NG2000/ABE, was developed; this formulation effectively enhanced the efficacy of abemaciclib by inducing ICD in vitro and in vivo." (PMID 41463246, 2025). "c-TRAK-TN (NCT03145961) evaluated immunotherapy in patients with triple negative breast cancer, DARE (NCT04567420) and LEADER (NCT03285412) are evaluating CDK4/6-inhibitors in ER+ disease, and ZEST (NCT04915755) is evaluating a PARP inhibitor in BRCA-related or triple negative breast cancer." (PMID 35223447, 2021). "Inhibition of CDK4/6 and CDK2 function using biochemical inhibitors suppresses the growth of triple negative breast cancer cells with low PPM1A, suggesting PPM1A as a biomarker to predict sensitivity to CDK inhibitors for more effective treatment of triple negative breast cancer." (PMID 31372497, 2019).
triple-negative breast carcinoma (continued). "Here we demonstrate that inhibition of CDK4/6 blocks breast tumour metastasis in the triple-negative breast cancer model, without affecting tumour growth." (PMID 28067227, 2017). "Similarly, the G1T28-04 clinical trial in triple-negative breast cancer revealed that trilaciclib did not compromise chemotherapy efficacy, regardless of CDK4/6 dependency." (PMID 40277746, 2025). "CDK4/6i, including abemaciclib, have received FDA approval for the treatment of advanced HR+, HER2− metastatic breast cancer but are also under investigation in multiple preclinical and clinical studies for the treatment of other solid tumors, including triple-negative breast cancer (TNBC)." (PMID 39930269, 2025). "Interestingly, CDK4/6 inhibition increased the radiosensitivity of both estrogen-positive and triple-negative breast cancers in RB wild-type but not in RB-null cells." (PMID 35625825, 2022). "The results of this study may be used as a baseline to gauge the real-world effect of new treatments targeting MBC introduced after the study period, such as the CDK4/6- and PI3K-inhibitors targeting HR-positive MBC, and immunotherapy for triple-negative breast cancer." (PMID 35597870, 2022). "For example, the lack of sensitivity of some triple-negative breast cancer cells may reflect both a decreased dependence on CDK4/6 activity for cell cycle entry (due to high cyclin E expression and CDK2 activity) and low p21 and/or p27 levels." (PMID 34784791, 2021). "However, despite the fact that TNBC may not be particularly sensitive to CDK4/6 inhibitors, CDK4/6 protein is indispensable for the proliferation of Rb wild-type triple-negative breast cancer." (PMID 35479314, 2022). "Moreover, Teo and colleagues have shown, that the CDK4/6 inhibitor ribociclib does not impair activation and cytotoxic potential of tumor-infiltrating CD8+ and CD4+ T cells in a triple-negative breast cancer mouse model." (PMID 36817127, 2023).
breast tumors (77 papers, 2006 to 2026). "This study reveals that CDK4/6i enhances intratumoral CD8+ T cell infiltration in breast tumors through functional reprogramming of tumor-associated macrophages (TAMs), facilitating indirect interactions between tumor and CD8+ T cells." (PMID 41082324, 2025). "Recent studies have shown RB1 inactivation as one of the potential mechanisms underlying resistance to CDK4/6 inhibitors in ER+ breast tumors." (PMID 40138429, 2025). "Prior to the implementation of CDK4/6 inhibitors in the adjuvant setting, ER loss at metastatic relapse was reported in up to 20–30% of luminal-like primary breast tumors." (PMID 41374423, 2025). "Loss of the tumor suppressor RB is an established mechanism of de novo and acquired resistance to CDK4/6i, and with the wider use of these agents as standard treatment, the population of patients with RB-deficient breast tumors is likely to rapidly increase." (PMID 38480701, 2024). "(2017) found that CDK4 T172 phosphorylation was most closely connected to breast tumors cell line susceptibility to the particular CDK4/6 inhibitor PD0332991 (palbociclib)." (PMID 38293701, 2023). "Loss of the tumor suppressor RB is an established mechanism of de novo and acquired resistance to CDK4/6i and with the wider use of these agents as standard of care, the population of patients with RB-deficient breast tumors is likely to rapidly increase." (PMID 37502925, 2023). "CDK4 amplification in breast tumors was linked to increased tumor cell proliferation, development of distant metastasis and poor clinical outcome." (PMID 37835528, 2023). "In regards to CDK4/6 inhibitors, AP-1 transcription factors were upregulated on treatment, which in turn were implicated with widespread enhancer activation in breast tumor models." (PMID 35774123, 2022). "Fortunately, the low incidence of Rb gene deletion/mutation (3.9%) in luminal-like breast tumors offers the possibility for CDK4/6 inhibition." (PMID 33364954, 2020). "Here, we report that the profile of post‐translational modification including T172 phosphorylation of CDK4 differs among breast tumors and associates with their subtypes and risk." (PMID 28566333, 2017). "In breast tumors, the alterations of the CDK4/pRb axis include amplification of CCND1 or CDK4, loss of CDKN2A/B or, less often, loss or mutation of pRb." (PMID 28566333, 2017). "In this study, we analyzed the association of CDK4 gene expression with the prognostic features and survival outcomes of breast tumors." (PMID 27759034, 2016). "Consistent with activation of CDK4/6 by NF1 loss, clinical data indicate that CDK4/6 kinase activities negatively correlate with NF1 protein levels in breast tumors." (PMID 41226361, 2025). "In patients with HR+/HER2− advanced breast tumors, cyclin-dependent kinase 4/6 inhibitors (CDK4/6 inhibitor), including palbociclib, ribociclib, and abemaciclib, have significantly improved the outcomes with a median PFS ranging from 14 to over 25 months." (PMID 40649034, 2025). "Collectively, these data indicated that XBP1s is highly expressed in HR+/HER2− breast tumors and exhibits a significant correlation with poor prognosis and resistance to the combination of CDK4/6 inhibitors and endocrine therapy in these patients." (PMID 40940685, 2025). "We used a combination of PD901 and Abemaciclib, a highly potent CDK4/6 inhibitor that was shown to be efficient in palbociclib-resistant ER+ breast tumours." (PMID 40764669, 2025). "For the treatment of breast tumors that include hormone receptors, CDK4 and CDK6 inhibitors have been authorized." (PMID 38231074, 2025). "This includes certain ER+ breast tumors for which CDK4/6i are currently used, as well as the highly aggressive TNBC subtype where CDK4/6i are currently being tested." (PMID 39826695, 2025).